IL16 (interleukin 16)
Diseases named in the same sentence as IL16 in open-access papers (continued):
Sharing a sentence is not in itself a finding about the gene and the disease.
gastric cancer (continued). "In the intestinal type and diffuse type of gastric cancer, the expression of 28 chemokines with their receptors such as CCL3 and CCL8 and 21 interleukins such as IL7 and IL16 demonstrated significantly statistical difference." (PMID 33426088, 2020). "To investigate the susceptibility and prognostic value of genetic variations of IL-16, TGFBR1 and TLR4 pathways to gastric cancer, we performed a case–control study combined a retrospective study in a Chinese population." (PMID 30479570, 2018). "We initially tried to use Western blotting an RT-qPCR to quantify IL-16 levels in gastric cancer patients without success." (PMID 35215488, 2022).
rheumatoid arthritis (15 papers, 2007 to 2025). A chronic, systemic autoimmune disorder characterized by inflammation in the synovial membranes and articular surfaces. "IL-16 is known to stimulate the expression of pro-inflammatory cytokines and has been associated with inflammatory diseases, such as rheumatoid arthritis." (PMID 35113938, 2022). "The importance of IL-16 in rheumatoid arthritis (RA) has been demonstrated by several investigators." (PMID 40529362, 2025). "More related to the context of our study that deals with inflammation, the role of IL-16 in rheumatoid arthritis is an issue widely considered." (PMID 39152360, 2024). "Interleukin-16 (IL-16), which is a proinflammatory cytokine, plays an important role in chronic inflammatory diseases, such as rheumatoid arthritis and inflammatory bowel disease." (PMID 35215488, 2022). "Although MIF has been shown to have a critical role in recruiting inflammatory immune cells in diseases such as rheumatoid arthritis, the biological role of IL-16 in autoimmune diseases still needs to be unraveled." (PMID 27551482, 2015). "In any case, our results together with those of the cited manuscript contribute to establish a solid experimental framework supporting a key role for IL-16 in clinical inflammatory diseases, as could be rheumatoid arthritis." (PMID 39152360, 2024). "Moreover, IL-16 is also involved in many autoimmune disease conditions such as inflammatory bowel disease, rheumatoid arthritis, and airway hyperresponsiveness." (PMID 25710036, 2015). "In this sense, the synthesis of IL-16 has been demonstrated in dendritic cells and, more related to inflammatory settings, it has been also described that fibroblasts may act as a source of IL-16 during rheumatoid arthritis." (PMID 39152360, 2024). "IL-16 is linked to inflammatory and autoimmune diseases, such as asthma, multiple sclerosis, systemic lupus erythematosus (SLE), and rheumatoid arthritis (RA), as well as inflammation-driven conditions like susceptibility to viral infections, depression, and cardiovascular diseases." (PMID 40003544, 2025). "IL-16’s regulatory role in inflammation has led to its study in autoimmune diseases such as asthma, inflammatory bowel disease, multiple sclerosis, systemic lupus erythematosus (SLE), and rheumatoid arthritis (RA)." (PMID 39408600, 2024). "IL-16 is classically considered as a CD4+ T cell chemoattractant cytokine whose role in inflammation has been demonstrated in a handful of inflammatory diseases such as experimental autoimmune encephalomyelitis, rheumatoid arthritis, and allergy." (PMID 30555461, 2018). "Unlike SLE, the clinical role of serum IL-16 remains controversial in rheumatoid arthritis (RA)." (PMID 32264927, 2020).
breast carcinoma (14 papers, 2014 to 2025). "Our findings demonstrate that IL-5, IL-7, and IL-16 are risk factors for HER2-positive breast cancer, with varying degrees of increased probability of HER2-positive breast cancer associated with elevated levels of these inflammatory cytokines." (PMID 37910571, 2023). "Consistent with our MR analysis findings, multiple meta-analyses and observational studies have demonstrated a robust association between the inflammatory cytokines IL-5 and IL-16, and the susceptibility to breast cancer." (PMID 37910571, 2023). "Importantly, our study is the first to demonstrate that IL-5, IL-7, and IL-16 play a significant role as risk factors in the development of HER2-positive breast cancer." (PMID 37910571, 2023). "Its role varies: in cutaneous T-cell lymphoma (CTCL), a pro-IL-16 mutation reduces p27KIP1, enhancing cell growth; in multiple myeloma (MM), IL-16 overexpression drives plasma cell proliferation; and in breast cancer, it recruits pro-tumor macrophages." (PMID 40003544, 2025). "The production of IL-16 correlates with the onset and progression of gastrointestinal tumors, breast cancer, cutaneous T cell lymphoma (CTCL), and multiple myeloma (MM)." (PMID 39408600, 2024). "In CTCL, a sequence mutation in pro-IL-16 reduces p27KIP1 levels, enhancing cell proliferation; in MM, overexpression of secreted IL-16 induces plasma cell proliferation; and in breast cancer, increased IL-16 recruits CD4+ pro-tumor macrophages." (PMID 39408600, 2024). "The results of the forward MR analysis showed a potential link between IL-5, IL-7, and IL-16 and an increased risk of HER2-positive breast cancer." (PMID 37910571, 2023). "Factors such as interleukins (IL-17, IL-12, IL-16, TGFβ, MCP-1, and GM-CSF have been associated with poor prognosis in breast cancer, attracting immune cells to the tumor and facilitating angiogenesis, inducing proliferation, metastasis, and drug resistance." (PMID 36968199, 2023). "Median plasma levels of IFN-α2 (174.27 vs. 199.64 pg/mL, p<0.008); IL-1Ra (418.73 vs. 503.33 pg/mL, p<0.02) and IL-16 (1931.86 vs. 3535.39 pg/mL, p<0.0001) were all significantly lower in early breast cancer patients compared to healthy controls." (PMID 35677046, 2022). "On the other hand, elevated expression of neutrophil-derived IL-16 is frequently found within the premetastatic niche of lungs in murine mouse models studying breast cancer metastasis." (PMID 35614362, 2022). "Few literature reports associated the role of IL-16 with the progression of different cancer types, one of those being breast cancer, but the presence of IL-16 at the breast cancer microenvironment tissue level has never been shown so far." (PMID 36539890, 2022). "Recently, several groups have shown that IL-16 display pro-tumoral activity in cutaneous T cell lymphoma, multiple myeloma and breast cancer." (PMID 25400927, 2014). "This association may be mediated through the CXCL, TGFb, VEGF, and IL16 signaling pathways, shedding light on the intricate interplay between mitochondrial dynamics and the tumor microenvironment in breast cancer progression." (PMID 38911373, 2024). "Therefore, it is essential to conduct further follow-up studies to delve deeper into the impact of interleukins (IL-5, IL-7, IL-16, and IL-10) on the two subtypes of breast cancer (HER2-positive and HER2-negative)." (PMID 37910571, 2023). "However, the precise mechanisms by which IL-5, IL-7, and IL-16 contribute to the initiation and metastasis of breast cancer, either via HER2 or other pathways, remain uncertain." (PMID 37910571, 2023). "IL16 induces the recruitment of macrophages in breast cancer." (PMID 36221095, 2022). "Moreover, in breast cancer, the upregulation of secreted IL-16 enhances the infiltration of monocytes into the tumor tissue." (PMID 24465869, 2014). "Serum IL-16 is a predictor for the development of distant metastases of breast cancer." (PMID 24465869, 2014).
breast carcinoma (continued). "Given that IL-16 is involved in T-cell recruitment and proliferation and modulates other immune responses, it might promote breast tumor immune surveillance and function as a tumor suppressor, accounting for its down-regulation in breast cancer seroma." (PMID 26361584, 2015). "Our study reveals a genetic correlation between IL-5, IL-7, IL-16, and HER2-positive breast cancer, providing valuable insights for future research on the pathogenesis and pharmacological intervention of HER2-positive breast cancer." (PMID 37910571, 2023). "IL-16, a cytokine known for its chemotactic and inflammatory properties, induces proliferation in cutaneous T-cell lymphoma T cells and plasma cells in multiple myeloma and recruits CD4+ protumor macrophages in breast cancer." (PMID 31737562, 2019).
multiple myeloma (14 papers, 2014 to 2026). "However, within the myeloma cell compartment, overexpression of IL16 relative to the CD4 receptor is associated with slightly better outcomes in the MMRF CoMMpass dataset (P = 0.038)." (PMID 36702834, 2023). "Our transient knockdown studies had previously indicated a role of IL-16 in promoting proliferation of myeloma cells and in our current study we asked the question whether there was an immediate association between the secretion of soluble IL-16 and the proliferation of the respective cells." (PMID 28512269, 2017). "IL-16 levels were directly correlated with gastrointestinal tumor progression and multiple myeloma; therefore, these malignant tumors are suggested targets for anti-IL-16 therapies." (PMID 32934782, 2020). "In consistent with anti-inflammatory property, Caterina Musolino and colleagues studied the IL-16 concentration in multiple myeloma before treatment and showed high levels of this cytokine in tumor locations." (PMID 29564064, 2018). "Very recently, we have described for the first time cytokine Interleukin-16 (IL-16) as a myeloma-promoting factor." (PMID 28512269, 2017). "In myeloma, plasma levels of IL-16 seem to correlate with the severity of the disease and the patients' prognosis." (PMID 28512269, 2017). "IL-16 concentrations in the BM of myeloma patients correlate with the number of malignant plasma cells and we have shown for the first time that the tumor cells themselves produce this cytokine." (PMID 28512269, 2017). "In order to further assess the functional consequences of IL-16 expression and secretion in MM we next developed and optimized a system for the stable knockdown of this cytokine in myeloma cells." (PMID 28512269, 2017). "Since all of our analyses had pointed to a central role of IL-16 in supporting the proliferation of myeloma cells, we next analyzed the growth behavior of MM cells after stable IL-16 knockdown." (PMID 28512269, 2017). "This constitutive secretion of IL-16 by most myeloma cell lines resulted in substantial levels of the cytokine in culture supernatants." (PMID 28512269, 2017). "Investigating the proliferative activity of myeloma cells after IL-16 silencing, however, we observed a significantly reduced cellular division rate." (PMID 28512269, 2017). "Overall, our results indicate an important role of anti-IL-16 therapies in the treatment of MM, in particular in combination with existing strategies targeting the bulk of myeloma cells." (PMID 28512269, 2017). "Clinical evidence from previous studies have reported mechanistic links of IL-16 to the progression of several forms of cancer such as cutaneous T cell lymphoma, multiple myeloma, breast, lung, and prostate." (PMID 26544695, 2015). "Although through different mechanisms, IL-16 induced proliferation of lymphocytes in T cell lymphomas and multiple myeloma and recruitment of pro-tumoral macrophages to breast tumors." (PMID 25400927, 2014). "In addition, we obtained preliminary data supporting a role of IL-16 in promoting the proliferation of myeloma cells." (PMID 28512269, 2017). "In conclusion, establishing a stable and inducible knockdown system, and thereby minimizing the effect of oscillating mRNA expression on knockdown efficiency and functional assays, we confirmed the important role of IL-16 as a proliferation-inducing cytokine in myeloma." (PMID 28512269, 2017). "IL-16 is growth-promoting in multiple myeloma and cutaneous T-cell lymphoma." (PMID 26361584, 2015). "IL16 has also been described as an important growth-promoting factor in multiple myeloma." (PMID 25613284, 2015). "In addition, myeloma cells with higher levels of CD9 expression proliferate rapidly via interleukin (IL)-16." (PMID 24520284, 2014). "Interestingly, the extent of release of IL-16 from a given myeloma cell line correlated with its proliferative activity, suggesting that this cytokine might indeed be an important pro-proliferative factor in MM." (PMID 28512269, 2017).
multiple myeloma (continued). "We have previously shown that myeloma cells strongly express IL-16, however, it has remained unclear whether only a certain fraction of the tumor bulk is producing this cytokine at any given timepoint and/or whether there are temporal variations in IL-16 synthesis." (PMID 28512269, 2017). "Most importantly, we show here that myeloma-propagating cells become entirely unable to form colonies in the absence of IL-16 suggesting that tumor-regenerating myeloma cells may be particularly susceptible to IL-16 neutralization." (PMID 28512269, 2017). "Overall, our results demonstrate that tumor-regenerating MM cells may be particularly susceptible to IL-16 neutralization, suggesting an important role of anti-IL-16 therapies in the treatment of MM, particularly in combination with existing strategies targeting the bulk of myeloma cells." (PMID 28512269, 2017). "Most importantly, we were able to demonstrate that myeloma-propagating cells become entirely unable to form colonies in the absence of IL-16." (PMID 28512269, 2017).
colorectal cancer (12 papers, 2014 to 2024). A primary or metastatic malignant neoplasm that affects the colon or rectum. "In our previous study we have shown that there is a significant relationship between the micro-RNA binding site polymorphism of the Il-16 gene and risk of colorectal cancer (CRC)." (PMID 25692036, 2014). "Similarly, research on colorectal cancer indicated that high IL-16 levels inhibited the cytotoxicity of CD8+ T cells in the immune microenvironment." (PMID 38933268, 2024). "Both IL-1α and IL-16 are key players of inflammation and colorectal cancer development." (PMID 36771338, 2023). "First, we observed the distribution of T-cell growth factor IL-2 and T-cell activator IL-16 in the peripheral blood and found that IL-2 concentrations were increased in the peripheral blood of patients with stage IV colorectal cancer (one-way ANOVA, IL-2 control vs stage IV, p = 0.0226)." (PMID 37063892, 2023). "Patients with stomach and colorectal cancers have been reported to have CRS evidenced by raised inflammatory markers, thrombocytopenia, elevated cytokine levels (IFN-γ/IL-2R/IL-18/IL-16/IL-10), and steroid responsiveness." (PMID 35891179, 2022). "One colorectal cancer patient with long-term anti-PD-1 monotherapy developed cytokine release syndrome (CRS) 5 days after receiving the Pfizer-BioNTech mRNA COVID-19 vaccine with evidence of increased inflammatory markers and elevated cytokine levels (IFN-γ, IL-2R, IL-18, IL-16, and IL-10)." (PMID 36033814, 2022).
diabetes (11 papers, 2013 to 2025). "Though we found negative correlations between fasting C-peptide and IL-1β, IL-2Rα, and IL-16 concentrations, it should be emphasized that the majority of patients in our study had long-term diabetes with undetectable beta-cell function." (PMID 37893217, 2023). "FABP9 was significantly correlated with “putative role of Tregs in COPD”, “breakdown of CD4+ T-cell peripheral tolerance in type 1 diabetes mellitus”, and “immune response_IL-16 signaling pathway” in the development of CRC." (PMID 34680577, 2021). "For example, the elevated levels of IL-16 in serum were reported in diabetes, metabolic syndrome and cardiovascular disease which are often associated with psoriasis." (PMID 27788245, 2016). "Multivariate logistic regression analysis was taken to analyze the effect of IL-16 rs8034928 and rs3848180 polymorphisms on the CAD risk, adjusted for sex, BMI, smoking, diabetes, hypertension, TC, HDL-C, LDL-C and TG." (PMID 24353682, 2013). "The combined effect of IL-16 rs8034928 and rs3848180 on the CAD risk was analyzed by multivariate logistic regression analysis, adjusted for sex, BMI, smoking, diabetes, hypertension, TC, HDL-C, LDL-C and TG." (PMID 24353682, 2013). "It is also reported that the increased expression of IL-16 in islets is related to the development of invasive insulitis, and neutralization of IL-16 might be a potential therapy for the prevention of diabetes." (PMID 31375554, 2019). "In a model of spontaneous diabetes in NOD female mice, blockade of IL-16 with neutralizing Abs prevented insulitis, destruction of insulin-producing pancreatic islets and inhibited development of type 1 diabetes." (PMID 40529362, 2025). "Among subjects with diabetes, those with TIR ≤ 70% had higher levels of IL-1α, IL-1β, IL-6, IL-12 p70, IL-16, LIF, M-CSF, MCP-1, MCP-3, RANTES, TNF-α, TNF-β, and b-NGF, and lower levels of IL-1α, IL-4, IL-10, GM-CSF, and MIF than individuals with TIR > 70%." (PMID 37893217, 2023). "In a diabetes mellitus (DM) model, T cells are attracted to the place of insulitis via CCL4, and inhibition of CCL4 and IL-16 were protective from DM." (PMID 40529362, 2025). "Additionally, non-obese mice genetically prone to diabetes are protected from developing diabetes when treated with an IL-16 neutralizing antibody." (PMID 38544694, 2024).